LIPG (lipase G, endothelial type)
Description:
Exerts both phospholipase and triglyceride lipase activities. More active as a phospholipase than a triglyceride lipase. Hydrolyzes triglycerides, both with short-chain fatty acyl groups (tributyrin) and long-chain fatty acyl groups (triolein) with similar levels of activity toward both types of substrates. Hydrolyzes high density lipoproteins (HDL) more efficiently than other lipoproteins.
Synonyms: EDL; EL; PRO719
Tractability: Small molecule: a high-quality ligand is known; it belongs to a druggable protein family. Antibody: UniProt places it where antibodies can reach, with high confidence; its Gene Ontology location is reachable by antibodies, with high confidence; UniProt predicts a signal peptide or a membrane-spanning region. PROTAC: a small molecule that binds it is known.
Target class: Enzyme; Hydrolase
Gene: Protein-coding gene on chromosome 18 (49,560,699 to 49,599,185, forward strand). Ensembl gene ENSG00000101670.
Subcellular location: Secreted
Pathways (Reactome):
Transport of small molecules: HDL remodeling
Gene Ontology:
Molecular function: phospholipase A1 activity; phospholipase activity; triacylglycerol lipase activity; lipoprotein lipase activity; carboxylic ester hydrolase activity; lipase activity
Biological process: cholesterol homeostasis; high-density lipoprotein particle remodeling; phospholipid homeostasis; positive regulation of cholesterol transport; positive regulation of high-density lipoprotein particle clearance; reverse cholesterol transport; fatty acid biosynthetic process; lipid metabolic process; phospholipid catabolic process; triglyceride catabolic process; response to nutrient
Cellular component: cell surface; early endosome; extracellular region; Golgi apparatus
Genetic constraint (gnomAD): Loss-of-function variants: 36 observed, 53.86 expected, observed/expected ratio (o/e) 0.67, 90% interval 0.51 to 0.88. The upper end of that interval is the gene's LOEUF score, 0.88, which puts it in group 3 of 6, group 1 being the genes least tolerant of losing a copy. Missense variants: 580 observed, 682.86 expected, observed/expected ratio (o/e) 0.85, 90% interval 0.79 to 0.91. Synonymous variants: 246 observed, 259.21 expected, observed/expected ratio (o/e) 0.95, 90% interval 0.85 to 1.05.
Homologues: Orthologues: chimpanzee LIPG (99% identical), macaque LIPG (97% identical), pig LIPG (88% identical), dog LIPG (86% identical), rabbit LIPG (85% identical), guinea pig LIPG (84% identical), mouse Lipg (80% identical), rat Lipg (78% identical), tropical clawed frog lipg (64% identical), zebrafish lipg (58% identical), Drosophila melanogaster CG6472 (21% identical), Drosophila melanogaster CG6296 (21% identical), and 13 more. Paralogues in human: LPL (43% identical), LIPC (40% identical), LIPH (28% identical), PNLIP (28% identical), LIPI (27% identical), PNLIPRP2 (27% identical), PNLIPRP1 (26% identical), PNLIPRP3 (26% identical), PLA1A (23% identical).
Diseases named in the same sentence as LIPG in open-access papers:
LIPG is named in the same sentence as 61 diseases in open-access papers, as found by Europe PMC text mining. Sharing a sentence is not in itself a finding about the gene and the disease. The quoted sentences say what the papers report.
breast carcinoma (22 papers, 2016 to 2025). "Tumor cells are able to maintain viability through metabolic reprogramming, and LIPG upregulation has previously been associated with enhanced proliferation in leukemia and breast cancer." (PMID 40426878, 2025). "LIPG, implicated in breast cancer, elevates interferon-stimulated genes (ISGs) expression, potentially by enhancing interferon signaling." (PMID 40426878, 2025). "Overexpression of LIPG in cluster 11 cells is significantly associated with tumor formation and metastasis in human breast cancer." (PMID 37736108, 2023). "The association between LIPG and risk of breast cancer was more pronounced among women with total cholesterol levels higher than 188 mg/dl, and among grades II and III breast cancer." (PMID 34001944, 2021). "Breast cancer risk increased with increasing levels of LIPG (Multivariable OR for the highest category (95% CI) 2.52 (1.11–5.81), P-trend = 0.037)." (PMID 34001944, 2021). "The risk of breast cancer increased with increasing levels of LIPG (multivariable OR for the highest category (95% CI) 2.52 (1.11–5.81), P-trend = 0.037)." (PMID 34001944, 2021). "We examined the LIPG-breast cancer association within our population-based case–control study from Galicia, Spain, BREOGAN (BREast Oncology GAlicia Network)." (PMID 34001944, 2021). "We also lacked sufficient follow-up data on survival or recurrence of breast cancer, precluding the examination of the LIPG-breast cancer association on survival or recurrence." (PMID 34001944, 2021). "Our findings indicate that elevated LIPG levels are associated with increased risk of breast cancer, especially Luminal A and HER2-negative breast cancers." (PMID 34001944, 2021). "In the present study, we found increased levels of LIPG to be associated with risk of breast cancer, especially breast cancer subtypes Luminal A and HER2-negative." (PMID 34001944, 2021). "We noticed that a basal level of ISG15 protein expression was detectable in parental MCF7 cells, suggesting that there is a LIPG-independent mechanism for sustaining ISG15 expression in LIPG-deficient luminal breast cancer cells." (PMID 29350614, 2018). "Ectopic overexpression of LIPG in LIPG-deficient luminal breast cancer cells promotes migration, stemness and basal/EMT features." (PMID 29350614, 2018). "Using data from the Breast Oncology Galician Network Study (BREOGAN), we will examine the effect of plasma endothelial lipase (LIPG) and OxLDL on the risk of breast cancer, overall and by major subtypes, as well as menopausal status, time of diagnosis, grade and morphology, in Spanish women." (PMID 34001944, 2021). "The LIPG-breast cancer association was restricted to Pre-menopausal breast cancer (Multivariable OR for the highest category (95% CI) 4.76 (0.94–28.77), P-trend = 0.06, and 1.79 (0.61–5.29), P-trend = 0.37, for Pre-menopausal and Post-menopausal breast cancer, respectively)." (PMID 34001944, 2021). "The LIPG-breast cancer association was restricted to women with high total cholesterol levels (Multivariable OR for the highest LIPG category (95% CI) 6.30 (2.13–20.05), P-trend = 0.018, and 0.65 (0.11–3.28), P-trend = 0.786, among women with high and low cholesterol levels, respectively)." (PMID 34001944, 2021). "The LIPG-breast cancer association was restricted to Pre-menopausal breast cancer (Multivariable OR for the highest LIPG category (95% CI) 4.76 (0.94–28.77), P-trend = 0.06, and 1.79 (0.61–5.29), P-trend = 0.372, for Pre-menopausal and Post-menopausal breast cancer, respectively)." (PMID 34001944, 2021). "The LIPG-breast cancer association was found to be associated with grades II and III breast cancers (Multivariable ORs for the highest category of LIPG (95% CI) 2.73 (1.02–7.69), P-trend = 0.057, and 1.90 (0.61–6.21), P-trend = 0.170, for grades II and III, and grade I breast cancers, respectively)." (PMID 34001944, 2021). "We also examined the LIPG-breast cancer association by tumor grade and histology." (PMID 34001944, 2021).
breast carcinoma (continued). "The LIPG-breast cancer association was restricted to Luminal A breast cancers (Multivariable OR for the highest LIPG category (95% CI) 3.70 (1.42–10.16), P-trend = 0.015, and 2.05 (0.63–7.22), P-trend = 0.311, for Luminal A and non-Luminal A breast cancers, respectively)." (PMID 34001944, 2021). "Finally, analyzing expression data of more than 1,000 breast carcinomas, Cadenas and colleagues showed that a small fraction of tumors overexpresses LIPG which was associated with shorter metastasis-free survival." (PMID 31423129, 2019). "In addition, since we lacked information on CRP or IL-6, further studies with these markers may shed light in the LIPG-breast cancer association." (PMID 34001944, 2021). "However, very limited data exists on the role of LIPG on the risk of breast cancer." (PMID 34001944, 2021). "However, very limited data exists on the role of LIPG on the risk of breast cancer in humans." (PMID 34001944, 2021). "In the previous study, LIPG downregulation decreased lipid synthesis capacity and proliferation of breast cancer (BCa) cells." (PMID 39946436, 2025). "Studies have demonstrated that LIPG plays an important role in the initiation and development of various malignant tumors such as breast cancer, gastric cancer, and testicular cancer." (PMID 39069526, 2024). "The study further showed that the downregulation of LIPG or FOXA in breast cancer resulted in reduced cancer cell proliferation and impaired intracellular lipid synthesis." (PMID 38605023, 2024). "Previously, it has been demonstrated that activation of LIPG in breast cancer cells promotes extracellular lipid uptake and facilitates tumor growth and progression." (PMID 38086791, 2023). "A downregulation of LIPG leads to reprogramming lipid metabolism and an inhibition of breast cancer cell growth." (PMID 35954428, 2022). "Taken together, our work demonstrates that developing LIPG inhibitors is a promising new therapeutic approach for the treatment of breast cancer." (PMID 35954428, 2022). "Several studies have demonstrated that LIPG promotes breast cancer initiation and progression though mediating the metabolism of intracellular lipids." (PMID 35954428, 2022). "Currently, a few synthetic LIPG inhibitors have been reported with inhibition efficiency in cell-free LIPG enzyme assays; however, these inhibitors cannot be used to treat breast cancer due to poor permeability in tumor cells." (PMID 35954428, 2022). "LIPG has been reported to support growth and survival of cancer cells by mediating lipid metabolism and/or adaptation to oxidative stress in breast cancer." (PMID 35108261, 2022). "A new gene, LIPG, was recently found to express and play a role in breast cancer proliferation, tumorigenicity, and metastasis." (PMID 35388653, 2022). "Previous studies revealed that a transcriptional factor, FoxA, and oxidative-stress-dependent AMPK contribute to the upregulation of LIPG in breast cancer cells." (PMID 35954428, 2022). "Aberrant expression of LIPG was found in several cancer types, including breast cancer, gastric cancer and testicular germ cell tumors." (PMID 35108261, 2022). "LIPG activity is essential for extracellular lipid uptake which is needed for subsequent proliferation of breast cancer cells." (PMID 34001944, 2021). "It has been shown that a decrease in LIPG inhibits breast cancer growth, implying that the incorporation of extracellular lipids, a function of LIPG, is crucial for the growth of cancer cells." (PMID 34001944, 2021). "We have previously analyzed the effect of circulating lipids (total cholesterol, LDL, HDL), and breast cancer stratified by LIPG levels and found opposing effects by LIPG levels." (PMID 34001944, 2021). "This means that LIPG activity is essential for lipid uptake which is needed for subsequent proliferation of breast cancer cells." (PMID 34001944, 2021).
breast carcinoma (continued). "The upregulated LIPG also results in the accumulation of intracellular lipid droplets in breast cancer cells, which protects against oxidative damage, finally supporting survival." (PMID 34405016, 2021). "Plasma LIPG and/or OxLDL were measured on 114 breast cancer cases and 82 controls from our case–control study, and were included in the present study." (PMID 34001944, 2021). "In a recent study, the upregulation of LIPG was found to be involved in breast cancer cell lipid addiction, thereby contributing to cancer proliferation." (PMID 32631391, 2020). "Our previous studies have shown that the enzymatic function of LIPG is required for promoting and sustaining the proliferation of breast cancer cells." (PMID 32488004, 2020). "Our findings provide novel insights into the oncogenic role of LIPG in breast cancer and its functional link to IFN-related signaling." (PMID 29350614, 2018). "Expression of LIPG mRNA in basal-like (n = 45), luminal-A (n = 46) and luminal-B (n = 25) breast cancers was analyzed in silico using the Gluck dataset collected in the Oncomine database." (PMID 29350614, 2018). "(D) ISG15 mRNA expression is positively correlated with LIPG expression in human basal-like breast cancers." (PMID 29350614, 2018). "Consistent with results from breast cancer tissues, LIPG was expressed at a higher level in basal-like cell lines when compared to Her2-amplified and luminal cell lines." (PMID 29350614, 2018). "Expression of LIPG mRNA in basal-like (n = 20), Her2-amplified (n = 15) and luminal (n = 13) breast cancer cell lines was analyzed in silico using the Hoeflich dataset retrieved from the Oncomine database." (PMID 29350614, 2018). "(A) LIPG mRNA expression in normal breast and different subtypes of breast cancers based on in silico analysis of the TCGA dataset." (PMID 29350614, 2018). "In this study, we have found that compared to other breast cancer subtypes, basal-like TNBCs preferentially overexpress endothelial lipase (LIPG), a member of the TG lipase gene family." (PMID 29350614, 2018). "Our findings from studying LIPG protein expression in breast cancer tissues and cell lines are consistent with the results from in silico analyses of public breast cancer datasets from the Oncomine database." (PMID 29350614, 2018). "By studying the catalytically inactive mutant of LIPG, we for the first time have revealed that LIPG possess both lipase-dependent and lipase-independent functions in breast cancer cells." (PMID 29350614, 2018). "To reveal the functional role of LIPG in breast cancer, we created the LIPG-overexpressing MCF7 cell line (MCF7-LIPG) whose parental cells lack LIPG expression." (PMID 29350614, 2018). "To validate these in silico analyses, we performed qRT-PCR analysis of LIPG mRNA expression in normal breast tissues (n = 6), TNBCs, and luminal breast cancers (LuBCs) positive for ER and PR markers (n = 8 for each subtype)." (PMID 29350614, 2018). "Our studies have shown that DTX3L, a ubiquitin E3 ligase essential for IFN-stimulated expression of ISGs, is required for protecting LIPG protein from proteasome-mediated degradation in breast cancer cells." (PMID 29350614, 2018). "(B) LIPG mRNA expression in different molecular subtypes of breast cancer classified based on the PAM50 gene expression signature." (PMID 29350614, 2018). "Here, the authors show that the proliferation of breast cancer cells depends upon the extracellular activity of the endothelial lipase enzyme LIPG whose expression is regulated by the FoxA family of transcription factors." (PMID 27045898, 2016). "We previously demonstrated that MCF-7 luminal breast cancer cells express lower levels of LIPG." (PMID 35954428, 2022). "To translate our findings into a therapeutic approach for breast cancer treatment, we identified a new LIPG inhibitor, cynaroside isolated from the herbal plant dandelion, and confirmed that the inhibition of LIPG is a promising strategy to combat TNBC tumor growth." (PMID 35954428, 2022).
breast carcinoma (continued). "Therefore, LIPG is a major player for lipid metabolic adaptations that breast cancer cells must undergo to continue proliferating." (PMID 34001944, 2021). "Because of the LIPG-HDL interrelationship, we also examined the HDL-breast cancer association." (PMID 34001944, 2021). "Experimental data showed that endothelial lipase (LIPG) is a crucial player in breast cancer." (PMID 34001944, 2021). "Breast cancer cells are dependent on a mechanism that allows them to extract lipid precursors from extracellular sources for intracellular lipid production, a process that is needed for cancer cells to be able to proliferate, and LIPG realizes this function." (PMID 34001944, 2021). "Moreover, a high LIPG expression was found in breast cancer and EL-mediated lipid uptake and lipid storage in response to oxidative stress promoted breast cancer growth and tumor progression." (PMID 33748195, 2021). "The LIPG-breast cancer association appeared to be restricted or more pronounced among women with non-postpartum breast cancer, those with high levels of total cholesterol, and those with grades II and III breast cancers." (PMID 34001944, 2021). "However, our previous studies have shown that ectopic overexpression of the catalytically inactive LIPG mutant also enhanced migration and stemness of luminal breast cancer cells to a greater degree than overexpression of wild-type LIPG16." (PMID 32488004, 2020). "Although it has been proposed that the phospholipase activity of LIPG and its function in importing lipid precursor species into cells are involved in promoting breast cancer cell proliferation, the exact role of LIPG in breast cancer remains largely unknown." (PMID 29350614, 2018). "Our studies showed that 68 kDa glycosylated LIPG is the predominant form in breast cancer cells." (PMID 29350614, 2018). "(E) LIPG mRNA expression in different molecular subtypes of breast cancer cell lines." (PMID 29350614, 2018). "Thus, although Luminal A and other breast cancer subtypes are treated with different treatments, it is not possible that any more pronounced effect of LIPG on the risk of Luminal A tumors was due to treatment differences." (PMID 34001944, 2021). "LIPG could be a new target for chemoprevention and treatment of breast cancer." (PMID 34001944, 2021). "As Luminal A and other breast cancer subtypes are treated with different chemotherapy treatments, it is tempting to think that the different effect of LIPG in Luminal A cancers, may be the result of the treatment used to treat that specific subtype of breast cancer." (PMID 34001944, 2021). "Therefore, we expected that XEN445 treatment may inhibit the proliferation of LIPG-expressing breast cancer cells." (PMID 32488004, 2020). "FOXA1 or FOXA2 triggers lipid metabolism reprogramming by maintaining high expression of endothelial lipase (LIPG) in breast cancer, allowing breast cancer cells to grow and extracellular lipids required for proliferation." (PMID 38605023, 2024). "The silencing of LIPG by shRNA leads to a reduction in OXPHOS, suggesting that LIPG is a key regulator of metabolism in breast cancer." (PMID 35954428, 2022). "However, no data exist on the role of LIPG on the risk of breast cancer in humans." (PMID 34001944, 2021). "In contrast, the phospholipase-independent function of LIPG is involved in oncogenic DTX3L-ISG15 signaling and promotes invasiveness, stemness and basal/EMT features of breast cancer cells." (PMID 32488004, 2020). "In contrast, the lipase-independent function is required for LIPG to enhance invasiveness, stemness and basal/EMT features of breast cancer cells." (PMID 29350614, 2018). "It has been shown that this rescue mechanism is not functional in breast cancer cells in the absence of LIPG or FoxA215." (PMID 34001944, 2021).